GREM1 (gremlin 1, DAN family BMP antagonist)
Diseases named in the same sentence as GREM1 in open-access papers (continued):
Sharing a sentence is not in itself a finding about the gene and the disease.
trichoepitheliomas (1 paper, 2017). "In particular, trichoepitheliomas (TEs) that often confound a differential diagnosis of BCCs have characteristic peritumoral stromal cells; this raise the question of whether there are any differences in stromal GREM1 expression between BCCs and TEs that can be used as potential diagnostic feature." (PMID 28346486, 2017).
ulcerative colitis (1 paper, 2025). An inflammatory bowel disease involving the mucosal surface of the large intestine and rectum. "The identified immune biomarkers (CCL18, DUOX2, GREM1, LCN2, and TNC) demonstrated strong diagnostic efficacy and are key immune genes for ulcerative colitis (UC)." (PMID 40584713, 2025). "The expression levels of core immune genes including CCL18, DUOX2, GREM1, LCN2, and TNC in ulcerative colitis models were detected by fluorescence q-PCR." (PMID 40584713, 2025).
cancer (113 papers, 2006 to 2026). A tumor composed of atypical neoplastic, often pleomorphic cells that invade other tissues. "Due to its high expression across multiple cancers and strong association with poor prognosis, GREM1 shows promise as a broadly applicable therapeutic target." (PMID 40066442, 2025). "Univariate Cox analysis across multiple cancer cohorts has shown that high GREM1 expression is significantly associated with poor prognosis, particularly in cancers like KIRC, KIRP, malignant MESO, PAAD, and STAD." (PMID 40066442, 2025). "Here, we reveal that cancer-associated fibroblasts-derived exosomes (CAF-exo) polarize macrophages towards an immunosuppressive phenotype through encapsulating Gremlin-1 (GREM1) in non-small cell lung cancer (NSCLC)." (PMID 40849639, 2025). "The strong stromal predilection of GREM1 is in line with previously reported high GREM1-levels in (cancer-associated) pancreatic fibroblasts." (PMID 40826447, 2025). "An early publication on GREM1 and cancer described GREM1 mRNA expression in cancer-associated stromal cells, linked to promotion of tumor cell proliferation." (PMID 40277903, 2025). "Overexpression of GREM1 has been linked to tumor progression in a range of cancers, where it is associated with enhanced stemness, increased metastasis, resistance to therapy, and poorer patient prognosis." (PMID 40277903, 2025). "GREM1 is a soluble, EV-associated protein that is upregulated in various types of tumors; it is involved in multiple biological processes that boost cancer development." (PMID 40069570, 2025). "Most data in the literature suggest that GREM1 is a “bad actor” in human cancer, with high levels of GREM1 associated with worse patient outcomes." (PMID 41033552, 2025). "This broad overexpression suggests that GREM1 plays a critical biological role across multiple cancers and is strongly associated with their initiation, progression, invasion, and prognosis." (PMID 40066442, 2025). "Interactions between GREM1+ cancer-associated fibroblasts (CAFs) and SPP/osteopontin+ macrophages were associated with poorer patient outcomes in gastric cancer." (PMID 41033552, 2025). "GREM1 encodes a protein of the bone morphogenic antagonistic family and has been linked to inflammation, fibrosis of numerous organs and cancers, including CRC." (PMID 40506516, 2025). "GREM1 expression in cancer is also associated with a fibrogenic, pro-epithelial to mesenchymal transition (EMT)-like environment." (PMID 40277903, 2025). "Changes in microRNAs have also been implicated as a potential mechanism of GREM1 upregulation in cancer." (PMID 40277903, 2025). "A major feature of subtype 3 was extensive infiltration of fibroblasts, scRNA-seq analysis showed that the GREM1+ cancer-associated fibroblasts (CAFs) percentage was significantly higher in this subtype." (PMID 36032084, 2022). "Cancer-associated fibroblasts (CAFs) express GREM1, which inhibits BMP signaling and accelerates tumor cell proliferation." (PMID 35883579, 2022). "Recent studies have shown that GREM1 is mainly secreted by fibroblast cells, including cancer-associated fibroblasts which can promote the proliferation of cancer cells." (PMID 33967807, 2021). "One of the up-regulated genes modulated in AYA-RMS is GREM1, that is known as a biomarker for cancer-associated myofibroblasts, with a potential role of micro-environmental modulation in AYA-RMS." (PMID 31533233, 2019). "Fine-mapping of the CRC associated variants in SCG5-GREM1 locus showed that a functional SNP acted as an allele-specific GREM1 enhancer and influenced cancer risk through differential CDX2 and TCF7L2 binding." (PMID 28977865, 2017). "GREM1 is a bone morphogenetic protein antagonist, and it is overexpressed in cancer-associated stromal cells in many solid tumors." (PMID 19187537, 2009). "In adulthood, upregulation of GREM1 expression has been linked to a range of human cancers." (PMID 40277903, 2025).
cancer (continued). "The availability of novel anti-GREM1 pharmaceutics should expand and improve the treatment options for clinicians aiming not only to kill cancer cells and reduce tumor burden, but also to specifically target CSCs and lower the cancer recurrence risk." (PMID 40277903, 2025). "The imbalance in the tumor microenvironment (TME) may contribute to the poor prognosis linked to GREM1 in cancer, as TME status directly affects immune cell infiltration." (PMID 40066442, 2025). "Furthermore, liver metastases also exhibited higher expression levels of a variety of cancer cell-associated genes (such as Hmga1 and Grem1) compared to primary tumors." (PMID 37190324, 2023). "HGF, HMOX1, ELN, and GREM1 genes associate with stromal fibrosis and contribute to malignancy through the proliferation of cancer-associated fibroblasts (CAFs) in various kinds of cancers." (PMID 37240308, 2023). "Moreover, GREM1 production by cancer-associated fibroblasts (CAFs) expedited the fibrogenic activation and facilitated breast cancer cell intravasation and extravasation in co-injection xenograft zebrafish models." (PMID 36091126, 2022). "GREM1, which encodes a member of the bone morphogenic protein antagonist family, is located at 15q13.3, and it is reported to be closely related to a variety of malignant tumors." (PMID 33962391, 2021). "In particular, modulated expression of GREM1 is found in cancer-associated stromal cells." (PMID 33976257, 2021). "Several studies have reported that GREM1 is associated with the function of cancer stem cells." (PMID 33287358, 2020). "However, the role of GREM1 in cancer progression and its underlying mechanisms remain poorly understood." (PMID 32572171, 2020). "Moreover, GREM1 has been associated with cancer fibroblasts in colonic and rectal smooth muscles and colonic crypt bases, and may participate in colorectal tumorigenesis through bone morphogenetic protein (BMP) signaling." (PMID 37249599, 2023). "p=service&cancer=lung) database showed that GREM1 expression in NSCLC patients predicted worse OS and first progression (FP)." (PMID 40849639, 2025). "GREM1 facilitates cell invasion and migration by regulating the EMT process and is closely associated with malignant tumor behaviors through enhanced cell proliferation." (PMID 40066442, 2025). "Given its role in promoting CSC properties and promoting tumor growth and cancer progression, GREM1 represents an attractive therapeutic target for cancer treatment." (PMID 40277903, 2025). "This indicates that GREM1 functions not only as a biomarker for specific cancers but also as a pan-cancer biomarker with extensive prognostic value." (PMID 40066442, 2025). "Pan-cancer studies have shown that GREM1 is consistently overexpressed across various cancers, including BRCA, HNSC, KIRC, KIRP, THCA, and UCEC." (PMID 40066442, 2025). "GREM1 is also a proangiogenic factor, suggesting a possible role in cancer development when upregulated." (PMID 40951278, 2025). "Considering the current scarcity of research on GREM1 in cancer studies, particularly regarding solid tumors, we conducted a systematic evaluation of GREM1 expression across various solid tumor types." (PMID 40066442, 2025). "In contrast to the overwhelming volume of publications implicating GREM1 as a “bad actor” in cancer, a small number of papers argue the opposite." (PMID 40277903, 2025). "GREM1 not only serves as a promising therapeutic target but also suggests new directions for cancer treatment strategies." (PMID 40066442, 2025). "Many reports have identified that high GREM1 levels correlate with poor patient prognosis in a range of human cancers." (PMID 40277903, 2025). "Overall, GREM1’s roles in cancer-related processes make it an intriguing protein for further investigation and a potential target for new therapeutic strategies." (PMID 40069570, 2025). "In established cancers, GREM1 expression is frequently upregulated in the desmoplastic stroma of a number of solid tumours." (PMID 40467544, 2025).
cancer (continued). "Previous studies have demonstrated that GREM1 plays a pivotal role in tumor progression, metastasis, and immune regulation across various cancers." (PMID 40066442, 2025). "Elevated GREM1 signaling in CAF subtypes in cancer contributes to epithelial–mesenchymal transition and the formation of mesenchymal cancer cells, increased solid tumor formation, invasion and metastasis." (PMID 40277903, 2025). "By further comparing the gene expressions for these groups, we found several known cancer or immune genes with high expression in the interactive zones (e.g., GREM1), suggesting the possible tumor-immune interactions in these zones." (PMID 38844966, 2024). "GREM1, a bone morphogenic protein (BMP) antagonist, is associated with proliferation, angiogenesis, and epithelial-to-mesenchymal transition of cancer cells." (PMID 39846783, 2024). "Although GREM1 has been reported to be involved in promoting various cancers, little has been reported about effects of GREM2 on cancer." (PMID 37880751, 2023). "Multiple reports identify the overexpression of GREM1 as a contributing factor in a broad range of cancers." (PMID 37615860, 2023). "Many mechanistic studies link the pro-tumorigenic effect of GREM1 to the promotion of a cancer stem-like and mesenchymal invasive phenotype and antagonism of BMP signaling in the stem cell niche, which facilitates stemness and self-renewal." (PMID 37615860, 2023). "The inhibitory effects of GREM1 on BMP signaling have been linked to these tumor-promoting effects, including facilitating cancer cell stemness and the activation of cancer-associated fibroblasts." (PMID 37615860, 2023). "The bone morphogenetic protein (BMP) antagonist Gremlin 1 (GREM1) can promote tumor cell proliferation and was found to be widely expressed by cancer-associated stromal cells of various human carcinomas." (PMID 37566084, 2023). "In this commentary, we will review these disparate findings and attempt to provide clarity around the role of GREM1 signaling in cancer." (PMID 37615860, 2023). "In contrast to the overwhelming consensus of GREM1 as a “bad actor” in human cancer, a small number of publications have presented data arguing the contrary." (PMID 37615860, 2023). "Many reviews have summarised the large volume of publications demonstrating elevated GREM1 levels as a feature of diverse human tumors, where GREM1 can be expressed in multiple cancer cells, but more frequently in CAFs." (PMID 37615860, 2023). "Several studies have reported the overexpression of GREM1 by cancer-related stromal cells, promoting tumor cell proliferation, which suggests that GREM1 is responsible for the specialized tumor microenvironment." (PMID 36091126, 2022). "By analyses of the GEPIA database, the upregulation of GREM1 gene expression in human cancers was of vital significance in the prognosis of multiple cancers." (PMID 36091126, 2022). "In summary, GREM1 is significantly upregulated in multiple cancers, including PDAC, which indicates a faster relapse and shorter survival for patients with PDAC." (PMID 36091126, 2022). "In pathological states, GREM1 is involved in processes such as organ fibrosis, inflammation and cancer." (PMID 35883579, 2022). "GREM1 has been reported to have a close relationship with a variety of malignant tumors in recent years." (PMID 33962391, 2021). "In this present study, two SNPs (MKNK1 rs8602, GREM1 rs10318) were previously reported in the context of cancer prognosis." (PMID 33658398, 2021). "GREM1 can induce the epithelial–mesenchymal transition (EMT) process in which epithelial cells become mobile mesenchymal cells to promote cancer cell migration and tumor growth." (PMID 33287358, 2020). "Multiple GREM1 duplications have been reported since and overexpression of GREM1 is thought to lead to polyp formation and cancer in the intestine." (PMID 32486027, 2020).
cancer (continued). "GREM1 can also increase activities of various transcription factors involved in cancer cell proliferation or tumor promotion." (PMID 33287358, 2020). "GREM1 is also involved in diverse pathological conditions such as organ fibrosis, inflammation, and cancer in BMP-dependent or -independent manners." (PMID 33287358, 2020). "GREM1 expression is found in many cancers and is thought to play important roles in regulative cell proliferation and survival of PCa." (PMID 33101546, 2020). "So far, very limited studies have clarified the mechanisms by which GREM1 is induced or how GREM1 affects cancer cell proliferation and growth." (PMID 32572171, 2020). "GREM1 is an antagonist of bone morphogenetic protein, which plays a key role in multiple biological processes, including cancer biology." (PMID 33107676, 2020). "Our study suggests that the GREM1–ERRα axis can serve as a potential therapeutic target in the management of cancer, especially ER-negative tumour." (PMID 32572171, 2020). "Analysis of GREM1 in tissue sections revealed that only the CAFs in close proximity to the cancer cells (tumor-stromal interface) showed high GREM1 RNA expression." (PMID 31533776, 2019). "Prompted by the profibrotic role of Grem1, we further explored the roles of Grem1 in fibroblast-mediated cancer cell invasion using a 3D spheroid model." (PMID 31533776, 2019). "Taken together, TGFβ secreted by cancer cells is the main determinant for inducing GREM1 expression by CAFs." (PMID 31533776, 2019). "High levels of GREM1 gene expression were observed in the stromal fibroblasts of many types of cancer, suggesting that CAFs are a potential source of Grem1." (PMID 31533776, 2019). "We therefore explored the possibility that fibroblasts express GREM1 in response to factors secreted by cancer or inflammatory cells." (PMID 31533776, 2019). "Of the malignant tumors, GREM1 positivity (score >2) was observed in 19 cases (23%) of BCCs, in 7 cases (42%) of SCCs, and in one case (20%) of MN." (PMID 28346486, 2017). "Based on these findings, we suggest that GREM1 expression is induced in myofibroblasts in the stroma, upon activation by invasive cancer cells or inflammation." (PMID 28346486, 2017). "Some in vitro studies have shown that GREM1 promotes proliferation and EMT in cancer cells; therefore, GREM1 expression is likely to be one of the properties of CAFs that promote the cancer progression." (PMID 28346486, 2017). "Further investigations are required to address the exact roles of GREM1 secreted by CAFs in the cancer microenvironment." (PMID 28346486, 2017). "Real-time PCR analysis showed that GREM1 expression was higher in malignant tumors, such as BCCs (P < 0.05) and SCCs (P < 0.01) than in benign tumors, such as EPs, HDAs, and SPAs." (PMID 28346486, 2017). "This suggests that GREM1-expressing fibroblasts are essential components of the cancer microenvironment." (PMID 28346486, 2017). "Given that subtle changes in distant regulatory elements result in low-penetrance of cancer susceptibility and play a role in tumor cell development, alterations in several loci of BMP4 at 14q22 and GREM1 at 15q13 affect TGFβ signaling." (PMID 24968322, 2014). "Gene expression profiling analysis identified SPP1, CTHRC1and GREM1 as potential biomarkers for early diagnosis of the cancer, and SPINK1 and BMP7 to distinguish between AC and SCC in small biopsies or in blood samples." (PMID 24299561, 2013). "Strategies aimed at inhibiting GREM1 expression or function could provide a means to not only target cancer cells but also disrupt the maintenance of CSCs and enhance chemotherapy effectiveness." (PMID 40277903, 2025). "Furthermore, in the MI group, fib-GREM1 was observed to significantly interact with MHC-II+ cancer cells through the COL1A1-ITGA2 and IL24-IL20RB axes, both of which are known to promote cancer cell stemness and support tumour aggressiveness." (PMID 41281745, 2025).